MRPS9 (mitochondrial ribosomal protein S9)
Synonyms: MRP-S9; S9mt; RPMS9; uS9m
Tractability: Small molecule: a structure with a bound ligand is known. PROTAC: ubiquitination databases record sites on it; its protein half-life has been measured.
Target class: Other cytosolic protein
Gene: Protein-coding gene on chromosome 2 (105,038,025 to 105,099,960, forward strand). Ensembl gene ENSG00000135972.
Subcellular location: Mitochondrion
Subcellular location (Human Protein Atlas): Mitochondria
Pathways (Reactome):
Metabolism of proteins: Mitochondrial ribosome-associated quality control; Mitochondrial translation elongation; Mitochondrial translation initiation; Mitochondrial translation termination
Gene Ontology:
Molecular function: protein binding; RNA binding; structural constituent of ribosome
Biological process: mitochondrial translation; translation
Cellular component: mitochondrion; mitochondrial inner membrane; mitochondrial small ribosomal subunit; ribosome
Genetic constraint (gnomAD): Loss-of-function variants: 29 observed, 31.37 expected, observed/expected ratio (o/e) 0.92, 90% interval 0.69 to 1.26. The upper end of that interval is the gene's LOEUF score, 1.26, which puts it in group 5 of 6, group 1 being the genes least tolerant of losing a copy. Missense variants: 279 observed, 298.33 expected, observed/expected ratio (o/e) 0.94, 90% interval 0.85 to 1.03. Synonymous variants: 103 observed, 107.21 expected, observed/expected ratio (o/e) 0.96, 90% interval 0.82 to 1.13.
Homologues: Orthologues: chimpanzee MRPS9 (99% identical), macaque MRPS9 (90% identical), dog MRPS9 (83% identical), pig MRPS9 (82% identical), rat Mrps9 (78% identical), mouse Mrps9 (77% identical), rabbit MRPS9 (76% identical), guinea pig MRPS9 (75% identical), tropical clawed frog mrps9 (62% identical), zebrafish mrps9 (55% identical), Drosophila melanogaster mRpS9 (42% identical), Caenorhabditis elegans mrps-9 (29% identical). Paralogues in human: RPS16 (13% identical).
Diseases named in the same sentence as MRPS9 in open-access papers:
MRPS9 is named in the same sentence as 4 diseases in open-access papers, as found by Europe PMC text mining. Sharing a sentence is not in itself a finding about the gene and the disease. The quoted sentences say what the papers report.
Intellectual disability (2 papers, 2016 to 2021). "In humans, a heterozygous de novo 360 kb deletion in chromosome band 2q12.1 resulting in the loss of the genes POU3F3 and MRPS9 was identified in a two-year-old boy with mild dysmorphic features of the head, mild motor delay and mild intellectual disability." (PMID 27003440, 2016). "uS9m (MRPS9)—A case study reported a 360 kb deletion in 2q12.2q12.1 affecting only two genes, POU3F3 and MRPS9, in a child presenting with intellectual disability and dysmorphic features." (PMID 33917098, 2021).
lung adenocarcinoma (1 paper, 2021). A carcinoma that arises from the lung and is characterized by the presence of malignant glandular epithelial cells. "In this study, a case of lung adenocarcinoma harboring a novel MRPS9-ALK fusion is reported." (PMID 34168990, 2021).
cancer (1 paper, 2024). A tumor composed of atypical neoplastic, often pleomorphic cells that invade other tissues. "Consistently, DepMap analysis revealed a strong correlation in gene effect between METTL17 and LRPPRC, MRPS9, MRPS22, and MRPS35, highlighting the significance of METTL17-associated cellular functions in cancer cell survival and ferroptosis defense." (PMID 38377789, 2024).
mitochondrial disease (1 paper, 2022). "Mitochondrial disease-causing mutations were found in thirteen small ribosomal subunit mitoribosomal proteins (MRPS1, MRPS2, MRPS6, MRPS7, MRPS9, MRPS11, MRPS14, MRPS16; MRPS22, MRPS23, MRPS25, MRPS34, MRPS39) and four large ribosomal mitochondrial proteins (MRPL3, MRPL12, MRPL24, MRPL44)." (PMID 36140315, 2022).